APOE (apolipoprotein E)
Diseases named in the same sentence as APOE in open-access papers (continued):
Sharing a sentence is not in itself a finding about the gene and the disease.
atherosclerosis (continued). "The study in Semenkovich’s laboratory demonstrated that UCP-1 generated ROS from vascular smooth muscle cells leads to elevated ROS, reduced NO bioavailability and accelerated atherosclerosis in mice on an ApoE deficient background." (PMID 24252331, 2013). "Atherosclerosis and apolipoprotein E ε4 (APOE4) genotype are risk factors for Alzheimer's disease (AD) and cardiovascular disease (CVD)." (PMID 26316992, 2013). "Appearance of atherosclerosis is similar to those in humans induced by ApoE deficiency called type III hyperlipoproteinemia." (PMID 22762010, 2012). "Apolipoprotein E (Apo E) polymorphism is accused of being the genetic risk factor for atherosclerosis." (PMID 22394699, 2012). "Apolipoprotein E (Apo E) polymorphism has been accused as being the responsible factor for development of atherosclerosis." (PMID 22394699, 2012). "Angiotensin II (ANG II) has been reported to accelerate atherosclerosis and induce aneurysms in hyperlipidemic apolipoprotein E deficient (apoE−/−) mice." (PMID 22448249, 2012). "In this study, we have provided evidence that the attenuation of atherosclerosis and decreased inflammatory responses in atherosclerotic lesions in BaffR.ApoE DKO mice is linked to a reduced B2 cell population." (PMID 22238605, 2012). "ApoE deficient mice (ApoE−/−) are a widely used model of atherosclerosis, hyperlipidemia and steatosis." (PMID 23029000, 2012). "In experimental coronary artery ligation models and atherosclerosis progression models by apolipoprotein-E deficiency, left ventricular myocardial infarction, and fibrosis were often found." (PMID 22830029, 2012). "We also examined the effect of ARE on atherosclerosis in the aortic endothelium of apolipoprotein E-deficient (apoE−/−) mice." (PMID 22536886, 2012). "Here, we have examined the role of BAFF-R in atherosclerosis using ApoE−/− mice deficient in BAFF-R." (PMID 22238605, 2012). "In an in vivo study, atherosclerosis was markedly impaired in mice deficient for both PKCβ and ApoE when compared to ApoE null mice." (PMID 23202940, 2012). "Administration of a murine monoclonal antibody (II-13) to amino acid residues 288 to 366 of HSP60 induced atherosclerosis in apolipoprotein E-deficient mice." (PMID 23304456, 2012). "In this regard, recent experimental data suggest that monoclonal anti-HMGB1 neutralizing antibodies reduce the development of atherosclerosis in apolipoprotein e-deficient mice." (PMID 23284878, 2012). "We sought to confirm these findings in animal models by evaluating the correlation of TEM levels with atherosclerosis extent in the aortic root of apolipoprotein E and low-density lipoprotein (LDL) receptor deficient animals." (PMID 23130116, 2012). "We previously reported that the progenitor cells in the adventitia contribute to atherosclerosis of vein grafts in ApoE-deficient mice." (PMID 22496883, 2012). "Ezetimibe is known to lower LDL and inflammation associated with the atherosclerosis in apoE−/− mice." (PMID 23119157, 2012). "The apolipoprotein E-deficient mouse has been the most widely used animal model of atherosclerosis because it rapidly develops severe hypercholesterolemia and spontaneous atherosclerotic lesions similar to those observed in humans." (PMID 22330242, 2012). "Apolipoprotein E deficient (ApoE−/−) mice have been widely used as animal models to study the pathophysiology of atherosclerosis." (PMID 22709928, 2012). "Diabetic ApoE/glutathione peroxidase-1 double KO mice show enhanced atherosclerosis compared to diabetic mice deficient in ApoE alone associated with enhanced VCAM-1 expression and macrophage recruitment." (PMID 22489274, 2012). "To elucidate the effect of an immunotoxin targeting FRβ on atherosclerosis, we determined the presence of FRβ-expressing macrophages in atherosclerotic lesions and administered the FRβ immunotoxin in apolipoprotein E–deficient mice." (PMID 23130174, 2012).
atherosclerosis (continued). "One year-old apoE-deficient mice having the dysfunctional LRP1 revealed a 3-fold decrease in spontaneous atherosclerosis development and a 2-fold reduction in LDL-cholesterol levels." (PMID 22701627, 2012). "The Apolipoprotein E deficient (ApoE−/−) mouse on a high-fat diet is a classical model of atherosclerosis, characterized by the presence of atherosclerotic plaques in extracranial vessels but not in cerebral arteries." (PMID 22709928, 2012). "Systemic administration of IL-2 to ApoE−/− mice has been shown to cause increased atherogenesis while anti-IL-2 antibodies decreased development of atherosclerosis." (PMID 22912809, 2012). "The large decrease in Fapb4 is of particular interest in that Fabp4 deficient mice on an apoE–/– background show a striking protection from atherosclerosis." (PMID 22276189, 2012). "The presence of the APOE-4 allele contributes to the phenotypic manifestation of atherosclerosis, brain amyloid angiopathy, and cerebral white matter damage." (PMID 22482072, 2012). "Defective binding of ApoE to heparan sulfate proteoglycans (HSPGs) is associated with increased risk of atherosclerosis and AD probably due to the inefficient clearance of lipoprotein remnants from the liver with negative consequences for neuronal repair." (PMID 22482072, 2012). "Diet-induced atherosclerosis in ApoE−/− mice was associated with marked neuroinflammatory responses in the brain, which were abolished in animals in which the IL-1 receptor was deleted." (PMID 23130147, 2012). "In summary, our in vivo studies demonstrate that inhibition of lp-PLA2 by darapladib does not decrease dyslipidemia but ameliorates the inflammatory burden, resulting in decrease of atherosclerosis in high-fat diet-fed ApoE-deficient mice." (PMID 21909350, 2011). "The suitability of this technique was assessed using three commonly used models of murine vascular injury: femoral artery wire-injury and ligation models of neointimal hyperplasia and the apolipoprotein E-deficient (apoE-/-) mouse model of atherosclerosis." (PMID 21379578, 2011). "We analyzed the development of heart failure in mice with chronic pressure overload induced by aortic constriction and compared the results with aged apolipoprotein E-deficient mice suffering from advanced atherosclerosis." (PMID 21711241, 2011). "ApoE-deficient mice have been extensively used to evaluate the efficacy of anti-atherogenic drugs and the mechanisms of atherosclerosis progression." (PMID 21909350, 2011). "Apolipoprotein E (ApoE), a cholesterol carrier associated with atherosclerosis, is a major risk factor for Alzheimer's disease (AD)." (PMID 21755005, 2011). "For example, the apoE-deficient mouse is the most widely used animal model of atherosclerosis even though apoE deficiency is extremely rare in humans." (PMID 21998599, 2011). "Mice that are deficient in apolipoprotein E (ApoE−/−) develop spontaneous atherosclerosis that narrows the vessel lumen, which leads to progressive restriction of blood flow at multiple arterial branches." (PMID 21677770, 2011). "Inhibition of lp-PLA2 by darapladib leads to attenuation of in vivo inflammation and decreased plaque formation in ApoE-deficient mice, supporting an anti-atherogenic role during the progression of atherosclerosis." (PMID 21909350, 2011). "When deficient in apolipoprotein E (apoE-/-) and fed a Western diet for 12 weeks, atherosclerosis-susceptible B6 mice developed significant hyperglycemia." (PMID 22204493, 2011). "In this study, we examined the effects of the lp-PLA2 inhibitor, darapladib, in ApoE-deficient mice to further establish its role in development of atherosclerosis." (PMID 21909350, 2011). "An n-6/n-3 ratio of ~1:1 in tissues has been reported to reduce atherosclerosis due to the inhibition of systemic and vascular inflammation in apolipoprotein E-deficient mice." (PMID 21999902, 2011).
atherosclerosis (continued). "Another study shows that overexpression of Cu/Zn-SOD and/or catalase in ApoE-deficient mice suppresses benzo (a) pyrene-accelerated atherosclerosis." (PMID 21600015, 2011). "Here we evaluated the effects of a specific lp-PLA2 inhibitor on atherosclerosis in ApoE-deficient mice and its associated mechanisms." (PMID 21909350, 2011). "Second, most studies used apolipoprotein E (ApoE)-deficient mice that spontaneously develop hyperlipidemia, which is a well-characterized risk factor for atherosclerosis." (PMID 21625524, 2011). "Atherosclerosis-susceptible B6.apoE-/- mice developed significant hyperglycemia on the high fat diet, whereas atherosclerosis-resistant BALB.apoE-/- mice did not." (PMID 22204493, 2011). "Apolipoprotein E-deficient (apoE−/−) mice develop spontaneous hyperlipidemia and atherosclerosis even when fed a low-fat diet." (PMID 22022387, 2011). "ER stress and APOE have been independently associated with neurodegenerative diseases and atherosclerosis." (PMID 22028770, 2011). "Inheritance of the ApoE allele ε4 increases the risk of developing both atherosclerosis and late-onset AD, suggesting a vascular component to the pathogenesis of neuronal degeneration in AD." (PMID 21439035, 2011). "ApoE-deficient mice spontaneously develop atherosclerosis with features similar to those observed in humans and is widely used to study the effect of diets on lipid metabolism and atherosclerosis." (PMID 21371300, 2011). "Despite its importance in lipid transport and atherosclerosis pathogenesis, apoE is associated with neurodegenerative disorders such as Alzheimer's disease (AD) and Parkinson disease, and autoimmune disorders such as multiple sclerosis and psoriasis." (PMID 21772670, 2011). "Clinical and experimental studies of atherosclerosis, including those using the apoE KO mouse model, support the concept that overabundance of ROS and/or a decline in antioxidant ability plays a causal role in atherosclerosis." (PMID 21896159, 2011). "Deficiency of apoE results in massive accumulation of remnant lipoproteins, leading to severe hypercholesterolemia and atherosclerosis in human and apoE knockout mice." (PMID 22074026, 2011). "Atherosclerosis was ameliorated in gAd Tg apoE-deficient mice, which was associated with decreased expression of class A scavenger receptor and TNF." (PMID 21829524, 2011). "We chose the ascending aorta as the site of measurement because it is known to have a predilection for development of atherosclerosis in ApoE−/− mice, and the plaque area of this site is closely correlated to total plaque burden of the entire aorta." (PMID 20864429, 2011). "Here, we used conditional gene targeting in mice to address in vivo, for the first time, the endothelial cell-specific function of p38α in atherosclerosis, in the apolipoprotein E deficient (ApoE−/−) mouse model." (PMID 21695272, 2011). "In this study, L-selectin deficient (L-sel−/−) mice were crossed with Apolipoprotein E deficient mice (ApoE−/−) to investigate the relevance of L-sel on both early and advanced stages of atherosclerosis." (PMID 21760899, 2011). "This study investigates the effects of endothelial- and macrophage-specific deficiency of p38α in atherosclerosis development, in Apolipoprotein E deficient (ApoE−/−) mice." (PMID 21695272, 2011). "In this brief review, we focus on the apolipoprotein E-deficient (apoE-/-) mouse, which is considered the best available model for human lipoprotein disorders and atherosclerosis." (PMID 22082357, 2011).
atherosclerosis (continued). "Using ovariectomized apoE-deficient mice, it was revealed that atherosclerosis was reduced when treated with E2 (6 μg/day) for 12 weeks." (PMID 21776259, 2011). "In this study we have evaluated the phenotype of MØ associated with progression of atherosclerosis in the apolipoprotein E (ApoE) knockout (KO) mouse model." (PMID 20111605, 2010). "We studied the molecular mechanisms involved in development of emphysema in atherosclerosis-prone apolipoprotein E-deficient (ApoE-/-) mice in response to CS exposure." (PMID 20663150, 2010). "Apolipoprotein E-deficient (apoE-/-) C57BL/6 (B6) mice are established models of atherosclerosis that develop advanced atherosclerotic lesions when kept on a high fat diet." (PMID 20482780, 2010). "In apolipoprotein E knockout mice (apoE-/-), which are deficient in apolipoprotein E and represent a model for atherosclerosis in humans, vasomotor function is inversely correlated with plaque-size, whereas it is not affected by hypercholesterolemia." (PMID 21054825, 2010). "We have previously reported that these animals, upon exposure to a high cholesterol diet, exhibit protection from the development of atherosclerosis in the presence of reduced inflammation on an apolipoprotein E (ApoE)-deficient background." (PMID 20463885, 2010). "The effects of hypercholesterolemia on vasomotricity in apolipoprotein E-deficient (ApoE) mice, a murine model of spontaneous atherosclerosis, are still unclear." (PMID 20482882, 2010). "Apolipoprotein E-deficient (ApoE-/-) mice develop atherosclerosis due to an accumulation of cholesterol ester-enriched particles in the blood resulting from a lack of triglyceride and cholesterol metabolism/lipid transport." (PMID 20663150, 2010). "Recent data have shown that treatment with ivabradine reduces oxidative stress, improves endothelial function, and prevents atherosclerosis in apolipoprotein E-deficient mice." (PMID 21188276, 2010). "The ApoE-deficient mouse is considered one of the most relevant models for atherosclerosis because this animal develops spontaneous arterial lesions." (PMID 20482882, 2010). "Although endothelial dysfunction has been considered one of the early steps in atherosclerosis, its occurrence in ApoE-deficient mice is still controversial." (PMID 20482882, 2010). "To explore further the consequences of PDZK1 deficiency in apoE KO mice on atherosclerosis and the heart, we subjected mice to a more severe, cholate-containing atherogenic diet (Paigen diet)." (PMID 19956623, 2009). "Earlier insights into the role of PCs in atherosclerosis were obtained from experiments in atherosclerosis-prone apolipoprotein E (ApoE−/−) deficient mice." (PMID 20407620, 2009). "Apolipoprotein E knockout (ApoE KO) mice are genetically predisposed to development of atherosclerosis due to inability to impaired catabolism of triglyceride-rich lipoproteins." (PMID 20003528, 2009). "Inoculation of CP, MP or both agents in C57BL/6 apoE KO male mice caused aggravation of experimental atherosclerosis induced by cholesterol-enriched diet, with distinct characteristics." (PMID 19744321, 2009). "Animal studies also support the proinflammatory and pro-atherogenic role of CRP, because administration of human CRP or over-expression of CRP in apolipoprotein E -deficient mice promotes the development of spontaneous atherosclerosis." (PMID 19240794, 2009). "In apoE knockout mice, administration of IL-18 has been associated with enhancement of atherosclerosis, whereas deficiency of IL-18 has been shown to reduce the extent of atherosclerosis." (PMID 19347053, 2009). "To investigate the role of Nrf2 in the development of atherosclerosis, we crossed Nrf2−/− mice with apoliporotein E-deficient (ApoE−/−) mice." (PMID 19023427, 2008). "Here we report an assessment of the role of the TLR2 pathway in atherosclerosis associated with a high-fat diet and/or bacteria in ApoE+/− mice." (PMID 18787704, 2008).
atherosclerosis (continued). "ApoE iKO is also useful in its own right as a novel model system for the study of molecular mechanisms underlying atherosclerosis progression and regression." (PMID 18464897, 2008). "Elegant studies in animal models, i.e. Factor V Leiden mice crossbred with apolipoprotein E–deficient mice, indicates that unregulated thrombin generation is particularly harmful during the later stages of atherosclerosis." (PMID 18253477, 2008). "For example, wefound that treatment with the dual PPARα/γ agonist, compound 3q, was associated with amarked increase in atherosclerosis in control apoE KO mice, while PPARγ and α agonistsused alone in this model were protective." (PMID 18288280, 2008). "Homozygosity for ApoE ε4 is associated with atherosclerosis and Alzheimer's disease whereas ApoE ε2 and ε3 tend to be protective." (PMID 18823563, 2008). "Reduction of lesion size in MCP-1−/− apoE−/− mice has implicated it in the apoE gene deleted mouse atherosclerosis model." (PMID 18579408, 2008). "Previous research suggested that Fcγ receptor deficiency protects against atherosclerosis in Apolipoprotein-E knockout mice." (PMID 18673543, 2008). "The in vivo relevance of these findings was assessed in an experimental model of atherosclerosis in the apolipoprotein E deficient (ApoE-/-) mice." (PMID 19088845, 2008). "Mice-deficient in apolipoprotein E (apoE−/−) spontaneously develop pronounced aortic lesions characteristic of atherosclerosis." (PMID 18560564, 2008). "Early work using ApoE−/− mice crossed with IFN-γ receptor–deficient mice suggested that IFN-γ promoted atherosclerosis and was critical in modulating the balance between TH1 (cellular immunity) and TH2 (humoral immunity) sub-sets of T cells." (PMID 18795166, 2008). "In mouse models of atherosclerosis IL-1ra inhibits the formation of intimal fatty streaks in apolipoprotein E-deficient mice, and IL-1β deficient mice when crossed onto an apo e-/- background have reduced atherosclerosis." (PMID 18298837, 2008). "In apolipoprotein-E deficient mice, which provide a valid research model for atherosclerosis, inactivation of the gene encoding TNFα significantly reduces the size of atheroma plaques." (PMID 17335569, 2007). "The most common animal model to examine atherosclerosis is the apolipoprotein E deficient mice model." (PMID 23675029, 2007). "In murine models of atherosclerosis, ApoE-/- mice, the consequences of inactivating the gene encoding CD36 remain contradictory: a decrease in the formation of atheroma plaques in one case, and an increase in the size of atheroma plaques in another." (PMID 17335569, 2007). "While Plg-/- mice with an apoE-/- background showed an accelerated development and progression of intimal lesions, Plg-/- mice were protected against atherosclerosis in association with transplantation." (PMID 15574198, 2004). "ACE inhibitors have been shown to inhibit atherosclerosis in apoE-deficient mice and in several other animal models but failed in low-density lipoprotein (LDL) receptor– deficient mice despite effective inhibition of the reninangiotensin- aldosterone system." (PMID 12745671, 2003). "In this animalmodel of atherosclerosis, we have demonstrated that diabetesleads to the production of an increased number of lipid and apoE–deficient chylomicron particles." (PMID 12458658, 2002). "Furthermore, the antagonist of the neuropeptide Y1 receptor increases the progression of atherosclerosis by the production of IL-12 in apoE-deficient mice." (PMID 40823653, 2025). "To investigate whether AEP is implicated in atherosclerosis onset, we employed APOE–/– mice fed with a high-fat diet (HFD) (Clinton/Cybulsky Rodent Diet D12108 with 1.25% cholesterol) for different time points." (PMID 40371638, 2025). "This may in part explain the discrepancy in the response to statin therapy, which has been effective in ApoE-deficient mice but exhibited controversial effects in human patients with atherosclerosis plaques." (PMID 41383646, 2025).